H19 (H19 imprinted maternally expressed transcript)
Diseases named in the same sentence as H19 in open-access papers (continued):
Sharing a sentence is not in itself a finding about the gene and the disease.
cancer (continued). "In summary, the rs2839698 G>A and rs2107425 C>T polymorphisms in lncRNA H19 may therefore play opposing roles during cancer development, and their effects may vary depending on cancer type and patient ethnicity." (PMID 28404885, 2017). "Therefore, in this meta-analysis, we examined the association between lncRNA H19 polymorphisms and cancer susceptibility in all relevant published studies." (PMID 28404885, 2017). "Since HCC and other cancer types are associated with global DNA hypomethylation 39, 40, 41, the link between H19 expression and promoter methylation remains unclear, and should be clarified in further studies." (PMID 31225433, 2017). "Furthermore, growing evidences suggests that polymorphisms in the H19 gene affect cancer development." (PMID 28404885, 2017). "Upregulation of lncRNA H19 expression is associated with an unfavorable prognosis in some cancers." (PMID 27926484, 2017). "We also summarized the results of the lncRNA H19 polymorphisms with cancer risk." (PMID 28159929, 2017). "There were many studies to investigate the SNPs within H19 associated with cancer susceptibility." (PMID 28159929, 2017). "Both LOI and LOH of H19 are associated with cancer carcinogenesis and progression." (PMID 27802187, 2017). "Despite these limitations, our meta-analysis indicated that the lncRNA lncRNA H19 rs2839698 G>A and rs2107425 C>T polymorphisms might play different role during cancer development." (PMID 28404885, 2017). "Targeting H19 in cancer therapy may reduce MDR1-associated drug resistance, as H19 knockdown has been shown to suppress MDR1 expression." (PMID 28933364, 2017). "Furthermore, genetic variants of lncRNA H19 have been shown to affect its expression and susceptibility to cancers." (PMID 27486980, 2016). "This meta-analysis provided evidence that H19 rs2107425 may modify general cancer susceptibility, while rs2839698 may modify cancer susceptibility based on ethnicity and type." (PMID 27732938, 2016). "Thus, we performed a meta-analysis to estimate the associations between H19 polymorphisms (rs2107425, rs2839698 and rs217727) and cancer risk." (PMID 27732938, 2016). "However, the underlying molecular mechanisms on the role of H19 in cancer progression and metastasis remained unclear." (PMID 27825121, 2016). "Recent analysis showed that H19 expression was associated with cancer metastasis." (PMID 27193186, 2016). "An increased level of H19 was also associated with poor clinical outcomes of cancer patients." (PMID 27825121, 2016). "Several SNPs in LSP1 and H19 were most likely associated with the risk of developing cancer." (PMID 26770289, 2016). "Thus, we performed a meta-analysis using currently published data to more precisely characterize the associations of rs2107425, rs2839698 and rs217727 in H19 lncRNA with cancer risks." (PMID 27732938, 2016). "H19 was found to be involved in cell cycle- and cancer-associated pathways." (PMID 26424084, 2015). "miR675, embedded in H19's first exon, had been linked to the development of human cancers." (PMID 26376677, 2015). "Since inflammation, especially chronic, can cause cancer and since H19 is a major player in many cancer types, the question arises whether H19 regulation/expression may change during the inflammatory process." (PMID 23429271, 2013). "Loss of imprinting at the H19 locus resulted in high H19 expression in various cancers." (PMID 23455466, 2013). "Likewise, loss of imprinting at the H19 locus resulted in high H19 expression in cancers of the esophagus, colon, liver, bladder and with hepatic metastases." (PMID 21489289, 2011).
cancer (continued). "Although the mechanisms underlying IGF2 LOI in human cancer remains unknown, it is likely to directly or indirectly involve the H19 ICR." (PMID 19737423, 2009). "Glycerophospholipid metabolism, pivotal for membrane biosynthesis and cellular signaling, has been previously implicated in cancer; herein, we extend this association into the realm of EVs, suggesting that alterations in this pathway could be mediated or regulated by lncRNA H19." (PMID 39594687, 2024). "Several lncRNAs, including Metastasis-Related Lung Adenocarcinoma Transcript 1 (MALAT1), H19 Imprinted Maternally Expressed Transcript (H19), and some others, have been shown to be candidate targets of promising therapeutic and diagnostic modalities for several cancers." (PMID 36578923, 2022). "In this way, increasing expression of H19 could downregulate E-cadherin (repressor of cell invasion and metastasis) and Nkd1 (inhibitor of Wnt/β-catenin signaling), causing the progression of cancer cells." (PMID 36246634, 2022). "Given the oncogenic roles of H19 and the functions of genetic variants in modulating the expression or structure of H19, increasing studies have been performed to examine the associations of single nucleotide polymorphisms (SNPs) in H19 with genetic susceptibility to cancers." (PMID 33800276, 2021). "However, until now, the whole picture of causality between H19 and cancer remains unclear The bioinformatics analysis may provide a feasible paradigm to understand the role of H19 from a more comprehensive angle." (PMID 33193379, 2020). "Furthermore, disruption of imprinting in somatic cells has been implicated in the pathogenesis of different cancers, like loss of imprinting within the H19/IGF2 imprinting control region in colorectal cancer, and gain of imprinting at 11p15 in hepatocellular carcinoma." (PMID 32487212, 2020). "A critical remaining question is whether the changes observed in IGF-II/H19 are a consequence of the genetic/epigenetic alterations that occur in neoplastic cells or whether epigenetic alteration in IGF-II/H19 predisposes tissues to the development of cancer." (PMID 31590432, 2019). "This meta-analysis revealed H19 rs217727 may influence cancer susceptibility." (PMID 31752724, 2019). "Therefore, the genetic variations of H19, especially in the promoter region may play a critical role in affecting the susceptibility to cancer." (PMID 31452627, 2019). "Overall, the study revealed that H19 rs217727 might increase the risk of cancer." (PMID 31752724, 2019). "Thus, the discovery of lncRNA H19 may be ascribed a major role in chemoresistance in cancer cells; the mechanism underlying NSCLC is yet unclear." (PMID 27911863, 2017). "Furthermore, variant genotypes of rs2839698 were associated with increased serum mRNA expression levels of H19 in cancer-free controls, suggesting a potential functional impact of this promoter SNP on mRNA levels, thus supporting a role in the susceptibility to GC." (PMID 25944697, 2015). "Among the numerous candidates, the long non-coding RNA H19 and its derivative miR-675 have been increasingly recognized as key regulators of metastatic dissemination in cancers of diverse tissue origins." (PMID 42041526, 2026). "Previous research has highlighted that H19 confers resistance to conventional therapies and promotes carcinogenesis through its oncogenic function in numerous cancers such as lung, bladder, breast, and gastrointestinal malignancies." (PMID 41521159, 2026). "In this study, we investigated the germline mutation alterations of ADAM6, SIX3, GNAS, NDUFV1, H19, DEFA4, and ZIM2 genes in 82 pediatric cancer patients treated with cisplatin." (PMID 41009448, 2025). "Knockdown of H19 mRNA induces the responsiveness and sensitivity of resistant cancer cells toward doxorubicin by increasing its accumulation and toxicity in both resistant and normal hepatoma cancer cells." (PMID 40352931, 2025).
cancer (continued). "Key lncRNAs associated with BC include H19, which promotes cancer cell proliferation, and MALAT1, which facilitates distant metastasis of cancer cells." (PMID 40313963, 2025). "Within this network, they found that H19, a lncRNA, increases the expression of cancer‐related mRNAs by competitively binding to various miRNAs, thereby activating the PI3K–Akt signaling pathway and promoting CRC progression." (PMID 40556338, 2025). "This context-dependent behavior of H19 emphasizes its multiple roles in cancer biology with a complex array of mechanisms." (PMID 40407591, 2025). "Specifically, one prominent lncRNA, LncRNA-H19 (H19), one of the first lncRNAs identified, has caught particular attention due to its role in tumorigenesis and cancer progression." (PMID 40885718, 2025). "For example, the oncogenic lncRNA H19 is abnormally overexpressed in various cancer types and promotes proliferation, metastasis, therapeutic resistance, and evasion of apoptosis." (PMID 40521243, 2025). "By binding to miR-675, H19 indirectly promotes P-gp expression and drug resistance in certain cancers." (PMID 40352931, 2025). "The role of HDACs and other epigenetic remodellers on H19 expression in pathological conditions has already been analyzed, especially in cancer experimental models." (PMID 40885718, 2025). "Only a few studies have addressed the role of H19 in OSCCs, and the results are inconsistent, similar to findings in other cancers." (PMID 39659621, 2024). "H19, a frequently upregulated lncRNA in various cancer types, has been extensively utilized by researchers to achieve cancer-specific expression of downstream sequences." (PMID 38681199, 2024). "The dynamic and versatile functions of H19 within the same cancer type further drives the message of lncRNA complexity, and genomic heterogeneity from patient-to-patient and cohort-to-cohort." (PMID 38785786, 2024). "H19 and FOXF1 adjacent non-coding developmental regulatory RNA (FENDRR) are oncogenic lncRNAs that are associated with cancer invasion, proliferation, and migration in various types of cancers." (PMID 38414063, 2024). "Along with the role of H19 in normal human development, there are pathologic conditions like cardiac muscle hypertrophy, osteoporosis and cancer that this lncRNA is known to take part." (PMID 38166752, 2024). "Han and coworkers (2018) observed that the downregulation of the lncRNA H19 expression levels increases the chemosensitivity of cancer cells and activates the Akt/phosphoAkt signaling pathway, resulting in cancer cell death." (PMID 39003454, 2024). "Upon upregulation of H19 in most cancer types, it competitively binds to miRNAs and prevents the formation of an RNA-induced silencing complex targeting downstream mRNAs." (PMID 38355574, 2024). "H19 can play differential roles depending on the tissue type and developmental stage; it is an oncogene in BC and is highly expressed in cancer tissues compared with normal tissues." (PMID 38773429, 2024). "In some cancers, H19 seems to induce epithelial-to-mesenchymal transition (EMT), with a decreased expression of epithelial markers and an increased expression of mesenchymal markers." (PMID 38785917, 2024). "H19 specifically has been denoted for its role in promoting cancer cell survival in the most adverse conditions; tumors with high H19 profiles substantially withstand hypoxic conditions and evade cell death pathways." (PMID 38785786, 2024). "A different research revealed that inhibiting the EMT and Wnt signaling pathway through knockdown of H19 not only enhances the rate of apoptosis and sensitivity to tamoxifen but also reduces the invasiveness of cancer cells." (PMID 38166752, 2024). "Apart from the established role of H19 in promoting cell growth, proliferation, invasion, migration, epithelial-mesenchymal transition (EMT), and metastasis, it has been recently discovered that H19 also inhibits programmed cell death (PCD) of cancer cells." (PMID 38355574, 2024).
cancer (continued). "MRP4 and MDR are the pivotal molecules responsible for conferring resistance to H19 in cancer cells." (PMID 38166752, 2024). "Studies not only reported an increased expression, but also demonstrated an oncogenic function of H19 in cancer." (PMID 38318212, 2024). "Given its abnormal expression levels and diverse functions in several human cancers, H19 has aroused extensive interest regarding its implications in disease pathophysiology and its potential application as a therapeutic target in cancer." (PMID 38355574, 2024). "H19 functions through a variety of mechanisms, including interactions with miRNAs and/or target proteins to maintain cancer characteristics." (PMID 38902391, 2024). "By directly acting on key molecules or indirectly altering the levels of downstream proteins associated with these signaling pathways, highly expressed H19 regulates PCD, thereby influencing cancer development." (PMID 38355574, 2024). "In our study, we identified six signature genes, namely TNFRSF11B, METTL7B, SSTR2, OXTR, CDKN2C, and H19 which have been extensively studied in the past and are known to play a significant role in cancer." (PMID 37713112, 2024). "Reports suggest the downregulation of H19 in cancer tissues and its function as a suppressor gene also exist." (PMID 38355574, 2024). "In this review, we summarize the mechanisms by which H19 regulates PCD in cancer cells through various signaling pathways, molecular mechanisms, and epigenetic modifications." (PMID 38355574, 2024). "lncRNA H19 is an oncofetal transcript pivotal in the development and progression of various cancers." (PMID 38794196, 2024). "The H19/miR-675 axis is also involved in the invasion and metastasis of cancer cells by targeting some mediators such as suppressors of cytokine signaling 5 (SOCS5) and regulating STAT3 function." (PMID 38559560, 2024). "Since its discovery, numerous studies have focused on the role of H19 in the pathogenesis of various types of cancer through different mechanisms, such as sponging miRNAs, interactions with proteins, and epigenetic modifications." (PMID 38355574, 2024). "There is a functional link between HIF-1α and H19 that determines H19 elevation in hypoxic cancer cells." (PMID 38987833, 2024). "Some studies have reported H19 re-expression in some types of cancer, such as the esophagus, colon, liver, and bladder." (PMID 38559560, 2024). "In conclusion, we summarize the role of H19 signaling via PCD in cancer chemoresistance, highlighting the promising research significance of H19 as a therapeutic target." (PMID 38355574, 2024). "H19 lncRNA is highly expressed in a variety of human cancers and overexpressed in approximately 70% of BC." (PMID 38773429, 2024). "H19, the first identified long non-coding RNA (lncRNA) with riboregulatory function, is one of the most extensively studied lncRNAs in cancer." (PMID 38505593, 2024). "In this manner, the analysis of exosomal H19 levels in serum was shown to be more sensitive and specific than the analysis of cancer antigen 15.3 (CA15.3) and carcinoembryonic antigen (CEA) levels in blood." (PMID 39148900, 2024). "Since then, H19 has been observed to be overexpressed in many tumors, including GC, and plays an essential role in cancer progression and metastasis." (PMID 39184399, 2024). "Studies have shown that H19 can promote the stemness of cancer stem cells (CSCs) and chemoresistance of CRC cells in CRC." (PMID 38294554, 2024). "H19 promotes cancer progression through the H19/miR-675/E2F transcription factor 1 (E2F-1) signaling pathway." (PMID 38559560, 2024). "We hope that our study will contribute to a broader understanding of H19 in cancer development and treatment." (PMID 38355574, 2024).
cancer (continued). "H19 (imprinted maternally expressed transcript), the first discovered lncRNA29 was the top significantly upregulated and is known to promote cancer stemness and paclitaxel resistance." (PMID 37012431, 2023). "The maternally imprinted oncofetal lncRNA H19, physiologically expressed during embryogenesis and down-regulated at birth, was demonstrated to be re-expressed in a variety of cancers and act through different mechanisms." (PMID 36674656, 2023). "lncRNA H19 is a highly conserved gene that has gained extensive research attention in the fields of cancer and cardiovascular disease." (PMID 36787444, 2023). "Understanding its conformation and protein-binding sites and performing co-fold analysis with H19 lncRNA further underscores the therapeutic importance of pre-miR-675 in cancer biology." (PMID 37624037, 2023). "H19 is a lncRNA firstly described as an oncofetal transcript, serving as a biomarker for cancers and a promising therapeutic target in human disorders." (PMID 37005676, 2023). "lncRNA H19 imprints maternally expressed transcripts and promotes EMT and metastasis in various cancers, and the downregulation of lncRNA H19 decreases liver and lung metastases in PC cells." (PMID 37384249, 2023). "In contrast, the downregulation of H19 reversed the chemotherapy resistance of CD133 + cancer stem cells by blocking the MAPK/ERK signaling pathway in HCC." (PMID 36960964, 2023). "Long non-coding RNA (lncRNA) H19 has essential roles in growth, migration, invasion, and metastasis ofmost cancers." (PMID 36680478, 2023). "The H-19 gene, mapped at the short arm of chromosome 11, is expressed in numerous cancers, especially PDAC." (PMID 37370843, 2023). "Both the H19 lncRNA and miR-675 are up-regulated in many types of cancers and by common triggers, but it is unclear how this occurs since miR-675 is processed at the expense of H19 lncRNA." (PMID 37508536, 2023). "For instance, the knockdown of H19 in resveratrol-treated cancer cells has been shown to enhance the effects of resveratrol on apoptosis." (PMID 37841928, 2023). "LncRNA H19 contributes to enhancing the growth and cell cycle of cancers and inducing EMT and, therefore, promotes metastasis." (PMID 38004379, 2023). "H19 and NEAT1 are also reported to be associated with the resistance of cancer cells to chemotherapeutic drugs including bortezomib and dexamethasone respectively." (PMID 36899924, 2023). "Although H19-mediated interaction with PTEN-targeting miRNAs, such as miR-19a-3p and miR-675, has been documented in previous years, the precise pathways in which cancer cell-derived exosomal H19 induces angiogenesis remains to be elucidated." (PMID 36905871, 2023). "H19 RNA is a long non-coding RNA and it is suspected to be involved in tumorigenesis, cancer progression, and metastasis." (PMID 37189829, 2023). "The aberrant upregulation of H19 in tumorigenesis has been well-documented in different types of human cancers, but the role of H19 in HCC appears more complex." (PMID 36960964, 2023). "To investigate the influence of Brevilin A on the pro-cancer function of lncRNA H19, we adopted Brevilin A (20 μM) to treat the cells transfected with lncRNA H19 overexpression plasmid for 24 hours." (PMID 37253635, 2023). "Upregulated tissue-specific expression of H19 was found in, e.g., breast, colorectal, and oesophageal cancers." (PMID 37189829, 2023). "LncRNA H19 has been reported to play an oncogenic role by promoting cell proliferation, motility, invasion, and metastasis, in many types of cancers." (PMID 36793075, 2023). "Exosomes secreted by cancer stem cells invade endothelial cells, deliver lncRNA H19 to their target cells, and stimulate HUVEC angiogenesis by synthesizing and releasing VEGF." (PMID 37007117, 2023). "Altogether, these lines of evidence suggest a novel regulatory pathway of H19/YAP/CDX2 in GC which can serve as a potential target for cancer therapy." (PMID 37005676, 2023).